VEGFA (vascular endothelial growth factor A)
Diseases named in the same sentence as VEGFA in open-access papers (continued):
Sharing a sentence is not in itself a finding about the gene and the disease.
chondrosarcoma (62 papers, 2002 to 2025). A malignant cartilaginous matrix-producing mesenchymal neoplasm arising from the bone and soft tissue. "VEGFA upregulated in chondrosarcoma cell lines and is associated with chondrosarcoma grade." (PMID 38762695, 2024). "Chondrosarcoma development may be linked to angiogenesis, which is principally elicited by vascular endothelial growth factor-A (VEGF-A)." (PMID 28465477, 2017). "Additional studies are necessary to further uncover the relationship between miR-6839-5p and VEGFA in chondrosarcoma cells." (PMID 38762695, 2024). "The relationship between miR-6839-5p and VEGFA will be further verified by dual luciferase reporter assay and by co-transfection of miR-6839-5p mimic and VEGFA plasmids in chondrosarcoma cells." (PMID 38762695, 2024). "Although chondrosarcoma staging increases VEGFA, it is difficult to use it as a biomarker because angiogenesis always occurs with the growth of the tumor and not with the malignant behavior." (PMID 38762695, 2024). "In contrast, adiponectin promotes the angiogenesis in human chondrosarcoma by increasing vascular endothelial growth factor-A expression." (PMID 27119501, 2016). "The CXCR4 ligand SDF-1α doubled secreted VEGFA under hypoxic conditions in human chondrosarcoma cell line and these effects were inhibited by CXCR4 siRNA." (PMID 24647809, 2014). "Consistently, we found the expression of angiogenic markers, VEGFA and CD31, was significantly reduced in the IDH1mut KO cell-derived tumors, suggesting that IDH1 mutation is associated with the angiogenic potential of chondrosarcoma cells." (PMID 35198082, 2022). "However, the relationship of adiponectin with vascular endothelial growth factor-A (VEGF-A) expression and angiogenesis in human chondrosarcoma is mostly unknown." (PMID 26468982, 2015). "The positive correlation between the miR-181a expression and VEGFA production in a non-epithelial tumor tissue was proposed through the scrutiny of human chondrosarcoma cells." (PMID 32571344, 2020).
infarction (61 papers, 2005 to 2025). A localised pathological necrosis of tissue resulting from obstruction of the blood supply usually by a thrombus, an embolus, or vascular torsion. "The results showed that the serum level of VEGFA in AMI group was slightly higher than that of sham group due to ischemic stimulation of the AMI condition, which induced VEGF‐mediated neovascularization in the border area of infarction myocardial." (PMID 30643722, 2019). "Astragaloside IV, a major active compound of Astragalus, may promote angiogenesis via the silencing regulatory protein 7 (SIRT7)/vascular endothelial growth factor A (VEGFA) signaling pathway to improve brain tissue damage postcerebral infarction." (PMID 40802347, 2025). "Therefore, our data demonstrate that implantation of AC-VEGFA-hMSCs promotes angiogenesis and decreases infarction size by stimulating VEGFA production in the rat MI model." (PMID 32616068, 2020).
acute myeloid leukemia (60 papers, 2007 to 2025). Acute myeloid leukemia (AML) is a group of neoplasms arising from precursor cells committed to the myeloid cell-line differentiation. "In acute myeloid leukemia, high expression of VEGFA was identified as an oncogenic factor, whose function may be reversed by SEMA3A competing for neuropilin." (PMID 31552163, 2019).
cardiac hypertrophy (60 papers, 2010 to 2025). "Heart problems are also significantly linked to the rise in VEGFA expression, which causes cardiac hypertrophy to proceed." (PMID 37521843, 2022). "We extracted an insulin-like growth factor 1 receptor-related subnetwork in cardiac hypertrophy and a vascular endothelial growth factor A-related subnetwork in AMI." (PMID 30514363, 2018). "We also extracted an insulin-like growth factor 1 receptor-related subnetwork in cardiac hypertrophy and a vascular endothelial growth factor A-related subnetwork in AMI." (PMID 30514363, 2018). "The IGFR1-related subnetwork in cardiac hypertrophy and the VEGFA-related subnetwork in AMI were extracted for analysis." (PMID 30514363, 2018). "Angiogenesis and End-MT may play important roles in cardiac hypertrophy and fibrosis, both of which are regulated by activated MR-induced upregulation of the VEGFA/VEGFR2 signaling pathway." (PMID 36185701, 2022). "Finally, we considered insulin-like growth factor 1 receptor and vascular endothelial growth factor A as two candidate drug targets by utilizing the cardiac hypertrophy and AMI pathways." (PMID 30514363, 2018).
malignant glioma (60 papers, 2004 to 2025). A grade III or grade IV glioma arising from the central nervous system. "Our data revealed that EFEMP1 is a favorable prognostic factor for GBM, has a tumor-suppressive effect in malignant glioma cells, and acts in the extracellular compartment via independent blocking of EGFR and AKT signaling pathways while also repressing VEGFA-induced angiogenesis." (PMID 21955618, 2011).
colitis (59 papers, 2011 to 2026). Inflammation of the colon. "Our results provide evidence that the VEGF signaling pathway was activated in the AA-induced colitis model; VEGFA, VEGFR2, Src, and eNOS protein expression levels were increased through a cascade reaction; and PI3K was overexpressed." (PMID 35620404, 2022). "It has been found that the overexpression of vascular endothelial growth factor-A (VEGF-A) in colitis mice increases angiogenesis in the intestinal mucosa and stimulates leukocyte adhesion, worsening the condition of mice, suggesting that IBD is accompanied by angiogenesis." (PMID 35873579, 2022). "Our results reinforced the idea that colonic VEGF and eNOS levels were higher than normal in AA-induced colitis; 900 mg/kg and 450 mg/kg of FMPs could inhibit the increase in VEGFA and eNOS concentrations, respectively." (PMID 35620404, 2022). "In addition, another study also demonstrated that P. notoginseng administration could promote repair of colonic mucosal injury and microvessels in a (DSS-) or iodoacetamide (IA)-induced rat colitis models through blocking VEGFA isoforms and Rap1GAP/TSP1 pathway." (PMID 38698858, 2024).
osteoporosis (58 papers, 2012 to 2026). A condition of reduced bone mass, with decreased cortical thickness and a decrease in the number and size of the trabeculae of cancellous bone (but normal chemical composition), resulting in increased fracture incidence. "This study identifies FMO4, PSMA4 and VEGFA as key genes associated with osteoporosis, analyses their molecular mechanisms and regulatory networks and elucidates their relationship with the disease." (PMID 40764749, 2025). "VEGFA expression correlated positively with osteoporosis risk, possibly via ER‐β–mediated signalling that promotes osteoblast apoptosis." (PMID 40764749, 2025). "In our study, elevated VEGFA expression was significantly associated with an increased risk of osteoporosis, suggesting a potential pathogenic role." (PMID 40764749, 2025). "A study demonstrated that in the osteoporosis group, VEGFA gene showed a significant association with osteoporosis." (PMID 35859791, 2022). "In the present analysis, some variants within three noteworthy candidates, which impinge upon endothelial function (eNOS, ACE and VEGFA), have shown significant impact on the risk of osteoporosis through different genetic models." (PMID 33499313, 2021). "Three genes—FMO4, PSMA4 and VEGFA—were significantly associated with osteoporosis risk." (PMID 40764749, 2025). "A model comprising risk scores of traditional risk factors in addition to that of susceptibility haplotype CTAAAT (eNOS gene) and GATA (VEGFA gene) is capable of being excellent predictor of osteoporosis, likelihood of which prompts future genetic studies to probe it." (PMID 33499313, 2021). "In conclusion, the present study has exposed three susceptible haplotypes (CTAAAT, ACDG and GATA) within eNOS, ACE and VEGFA genes, which manifest in multiplicative and dominant mode for inflicting endothelial-associated osteoporosis risk in postmenopausal women." (PMID 33499313, 2021). "In particular, the VEGFA gene, which differed significantly in the osteoporosis BRONJ, is a member of previous well known risk gene families in ONJ, VEGF which is a growth factor that plays an important role in angiogenesis, vasculogenesis, and epithelial cell growth." (PMID 31747953, 2019). "In the osteoporosis group, VEGFA, DFFA, and FAM193A genes showed a significant association." (PMID 31747953, 2019). "It was reported that VEGFA regulates tumors, idiopathic membranous nephropathy, and osteoporosis through modulating angiogenesis." (PMID 40166052, 2025). "These immune populations are known to modulate inflammation, bone resorption and remodelling, reinforcing the immunomodulatory relevance of FMO4, PSMA4 and VEGFA in osteoporosis pathophysiology." (PMID 40764749, 2025). "This study identified key genes linked to osteoporosis, such as FMO4, PSMA4 and VEGFA, and explored their potential molecular mechanisms and regulatory networks." (PMID 40764749, 2025). "FMO4 and NOV were associated with a decreased risk of osteoporosis, whereas MAP2K5, PSMA4, SCARB1 and VEGFA were linked to an increased risk." (PMID 40764749, 2025). "The analysis revealed that FMO4 and PSMA4 were consistently downregulated in osteoporosis patients, whereas VEGFA exhibited significantly increased expression levels." (PMID 40764749, 2025). "According to a recent study, the administration of melatonin has been found to enhance angiogenesis mediated by BMMSCs by increasing the levels of VEGFA and expedite the repair of tibia bone defects in rats with osteoporosis." (PMID 38333049, 2024). "After analyzing microarray data and careful verification, they found that patients with osteoporosis had higher miR-16-5p and lower VEGFA levels." (PMID 37251576, 2023). "First, we did not perform in vivo experiments to determine the role of miR-16-5p/VEGFA in osteoporosis." (PMID 32427128, 2020). "QRT-PCR analysis showed that VEGFA mRNA levels were significantly reduced in osteoporosis patients compared to healthy subjects (n=10 per group; p < 0.001)." (PMID 32427128, 2020).
osteoporosis (continued). "QRT-PCR analysis of serum samples showed significantly high miR-16-5p levels and significantly reduced VEGFA levels in the osteoporosis patients compared with the healthy subjects." (PMID 32427128, 2020). "Upregulation of VEGFA induced angiogenesis and may serve as a novel target for treating osteoporosis." (PMID 40166052, 2025). "Pathway enrichment analyses indicated that FMO4, PSMA4 and VEGFA may influence osteoporosis progression through several critical signalling pathways, including calcium signalling, Wnt/β‐catenin, PI3K/Akt and Hedgehog signalling." (PMID 40764749, 2025). "In this study, we systematically identified VEGFA, PSMA4 and FMO4 as genes significantly associated with osteoporosis risk using MR, and explored their expression patterns using single‐cell RNA sequencing (scRNA‐seq) data from osteoporosis patients." (PMID 40764749, 2025). "Therefore, we aimed to evaluate the association between VEGFA polymorphisms and bisphosphonate-related ONJ occurrence in osteoporosis patients taking bisphosphonates, and we used supervised machine learning to build predictive models for BRONJ occurrence." (PMID 34200782, 2021). "Furthermore, we showed that miR-16-5p levels were upregulated and VEGFA levels were downregulated in osteoporosis patients." (PMID 32427128, 2020). "Several studies show that VEGFA plays an important role in osteoporosis." (PMID 32427128, 2020). "This suggests that VEGFA levels correlate with osteoporosis progression." (PMID 32427128, 2020). "Therefore, miR-16-5p/VEGFA axis is a potential therapeutic target for postmenopause-related osteoporosis." (PMID 32427128, 2020). "Excluding genes without known specific functions (CDC27 and TNRC18), ARID2, HEBP1, LTBP1, and PLVAP were the only significant differences in the cancer group revealed by the gene-score methodology, while DFFA, FAM193A, and VEGFA were the only significant differences in the osteoporosis group." (PMID 31747953, 2019). "This suggested that the related target molecules had an important role in GCK-treated osteoporosis, especially for the targets STAT3, PIK3R1, VEGFA, JAK2 and MAP2K1." (PMID 36430397, 2022). "In osteoporosis BRONJ group, we identified the VEGFA gene which is known to play a significant role in angiogenesis was also found in previous studies to be associated with the risk of ONJ." (PMID 31747953, 2019). "On the other hand, in the osteoporosis BRONJ with a relatively long-term exposure to BPs (42.7 ± 46.3 months), there were no more candidate genes to explain the pathophysiology besides VEGFA." (PMID 31747953, 2019). "Moreover, through directly targeting VEGFA, MIR-16-5P mitigated the symptom of postmenopausal women with osteoporosis." (PMID 37089711, 2023). "Postmenopausal patients with osteoporosis showed higher miR-16-5p and lower VEGFA levels than those without osteoporosis (n=10 each)." (PMID 32427128, 2020).
amyotrophic lateral sclerosis (57 papers, 2007 to 2025). Amyotrophic lateral sclerosis (ALS) is a neurodegenerative disease characterized by progressive muscular paralysis reflecting degeneration of motor neurons in the primary motor cortex, corticospinal tracts, brainstem and spinal cord. "Furthermore, VEGFA is involved in angiogenesis and is also implicated in development of amyotrophic lateral sclerosis (ALS)." (PMID 23110080, 2012). "We have earlier shown that protein levels of vascular endothelial growth factor-A (VEGF-A) and chemokine ligand-2 (CCL2) were elevated in Indian amyotrophic lateral sclerosis (ALS) patients." (PMID 21906274, 2011). "Vascular endothelial growth factor-A (VEGF-A) and chemokne ligand-2 (CCL2) levels have been examined in Amyotrophic Lateral Sclerosis (ALS) patients in Western countries." (PMID 21569455, 2011). "Remarkably, VEGFA administered at neuroprotective doses in an amyotrophic lateral sclerosis (ALS) rat model preserved motor neurons without significant vascular effects." (PMID 40050849, 2025).
head and neck cancer (56 papers, 2002 to 2026). A primary or metastatic malignant neoplasm affecting the head and neck. "We aimed to investigate if miRNAs hsa-miR-17-5p, hsa-miR-140-5p, and hsa-miR-874-3p could interfere in VEGFA, KRAS, and NFE2L2 expression in cell lines derived from head and neck cancer (HNC)." (PMID 35806488, 2022).
oral squamous cell carcinoma (56 papers, 2010 to 2026). "The increase in HIF1A and VEGFA factors was shown to be significantly, directly, and positively associated with increased malignancy in other types of cancer, e.g., oral squamous cell carcinoma." (PMID 39888575, 2026). "VEGFA encoded vascular endothelial growth factor A; many researchers reported that it was upregulated in oral squamous cell carcinomas." (PMID 35036428, 2022). "Zhang CZ observed that LINC00668 exerts its oncogenic effects in oral squamous cell carcinoma (OSCC) partially via sponging miR-297 and activating VEGFA, which may be a negative prognostic factor." (PMID 30971296, 2019).
uveitis (56 papers, 2011 to 2026). An inflammatory process affecting a part of or the entire uvea. "Neovascularisation is not a common feature in NIU, however, detection of the major angiogenic factor—vascular endothelial growth factor A (VEGF-A)—in intraocular fluids in animal models of uveitis may be an indication for a role for this cytokine in a highly inflammatory condition." (PMID 33671954, 2021).
Cirrhosis (55 papers, 2007 to 2026). A chronic disorder of the liver in which liver tissue becomes scarred and is partially replaced by regenerative nodules and fibrotic tissue resulting in loss of liver function. "TGF-β is anti-inflammatory and involved in inhibiting apoptosis, while TNF-α, IL-8, FGF2, and VEGFA are involved in hepatic injury or cirrhosis through cell proliferative and angiogenic activities." (PMID 41219858, 2025). "In patients with HCV-associated cirrhosis and HCC, several angiogenesis soluble factors were significantly upregulated in the blood plasma, including TIMP-1, TIMP-2, HGF, angiopoietin 1, angiopoietin 2, VEGFA, IP-10, PDGF, KGF and FGF." (PMID 33801181, 2021). "Botanical drugs and gut microbiota target MAPK1, VEGFA, STAT3, AKT1, RELA, JUN, and ESR1 in the treatment of hepatitis B cirrhosis, and their combined use has shown promise for cirrhosis treatment." (PMID 38029250, 2023).
small cell lung carcinoma (55 papers, 2006 to 2025). Small cell lung cancer (SCLC) is a highly aggressive malignant neoplasm, accounting for 10-15% of lung cancer cases, characterized byrapid growth, and early metastasis. "In addition, it regulates Etk expression by sponging miR‐218 to promote drug resistance and progression of small cell lung cancer, and it promotes angiogenesis and progression of lung squamous cell carcinoma via the regulation of VEGFA expression by sponging miR‐511‐5p." (PMID 36606322, 2023).
astrocytoma (54 papers, 2000 to 2026). "Moreover, acquired gains of 12 genes (including VEGFA) on 6p during relapse were associated with unfavorable prognosis for lower grade astrocytoma patients." (PMID 37741941, 2023). "Specifically, we found that gain of VEGFA in lower grade astrocytoma patients had significant prognostic value and the expression of VEGFA was further validated to be upgraded at recurrence by IHC." (PMID 37741941, 2023). "Collectively, these results indicated that VEGFA was a prognostic marker specifically within the context of recurrent lower grade astrocytoma." (PMID 37741941, 2023). "In the case of lower grade astrocytoma, the acquisition of VEGFA gain upon recurrence was found to be significantly correlated with shorter overall survival (log-rank test, P = 0.04)." (PMID 37741941, 2023). "Specially, the presence of VEGFA gain indicates an unfavorable prognosis in recurrent lower grade astrocytoma patients." (PMID 37741941, 2023). "In addition, the close association observed here between increased VEGFA and COL1A2, COL3A1 and COL1A1 expression in GBM, might also contribute to explain the effect of VEGFA on inducing collagenase expression and remodeling the tumor microenvironment in malignant astrocytomas (i.e. GBM)." (PMID 32647207, 2020).
edema (54 papers, 2006 to 2026). An abnormal accumulation of fluid beneath the skin, or in one or more cavities of the body. "Our results also revealed that the vascular endothelial growth factor A (VEGFA) was a part of the “RAP1 signaling pathway” profile, and its high expression is known to be associated with peritumoral brain edema." (PMID 36937440, 2023).
fibrosarcoma (54 papers, 2001 to 2026). A malignant mesenchymal fibroblastic neoplasm affecting the soft tissue and bone. "Previous studies have shown that the expression of soluble VEGFA subtypes can increase the metastasis of fibrosarcoma through multiple mechanisms." (PMID 38240704, 2024). "We used a mouse fibrosarcoma cell line, fs120, which expresses the VEGF120 isoform of vascular endothelial growth factor A (VEGF-A) in isolation." (PMID 29221156, 2017). "Specifically, VEGFA is universally detected in human myxoid liposarcoma tumors, and FUS-CHOP has been shown to upregulate VEGFR1 when expressed in HT1080 human fibrosarcoma cells." (PMID 27822137, 2016). "Unlike VEGFA-164 and VEGFA-120, VEGFA-188 (mouse counterparts of human VEGFA-165, VEGFA-121, and VEGFA-189 isoforms, respectively) does not affect fibrosarcoma cells proliferation and migration, but induces apoptosis." (PMID 29888133, 2018).